TYR (tyrosinase)
Diseases named in the same sentence as TYR in open-access papers (continued):
Sharing a sentence is not in itself a finding about the gene and the disease.
melanoma (continued). "Additionally, Sahin and collaborators (2020) conducted phase I trials testing the melanoma liposomal RNA vaccine (BNT111) against four non-mutated antigens, including TPTE, Tyrosinase, melanoma-associated antigen A3 (MAGE-A3), and New York Esophageal Squamous Cell Carcinoma 1 (NY-ESO-1)." (PMID 38546751, 2024). "Furthermore, it was found that FB-ChiBai significantly attenuated melanin production, tyrosinase activities, and melanogenesis-related signaling pathways and reduced the nuclear translocation and promoter binding activities of MITF in B16F0 murine melanoma cells." (PMID 38140115, 2023). "Interestingly, SMILE was significantly downregulated in melanoma tissues (p = 0.0003) compared to normal tissues, whereas the expression of the melanocyte-specific form of MITF (MITF-M) and its melanogenic target genes such as TYR and TRP1 was upregulated as expected." (PMID 36499416, 2022). "Therefore, one can envision use of well-established inhibitors of melanogenesis such as N-phenylthiourea, D-penicillamine (copper chelator), kojic acid, or other non-toxic inhibitors of tyrosinase to enhance radio-, chemo-, or immunotherapy of melanotic melanomas." (PMID 35359389, 2022). "Moreover, even when the TYR assay was performed using cellular TYR from MNT-1 human melanoma cells, deoxyvasicinone was unable to inhibit the enzymatic activity of cellular TYR, demonstrating that deoxyvasicinone did not directly inhibit TYR enzymatic activity." (PMID 35200684, 2022). "However, the inhibitors of PI3K/AKT and ERK, LY294002 and PD98059, could not affect the increased expression of MITF and TYR by 5-HT treatment in B16F10 melanoma cells." (PMID 32961761, 2020). "No alteration of basal tyrosinase expression was observed after 24 h treatment of human melanoma cells with the inhibitor, but preliminary evidence suggested LCAME might impair the induction of tyrosinase expression in cells stimulated with α-melanocyte-stimulating hormone." (PMID 30042336, 2018). "Although no potent tyrosinase inhibitors have been isolated from citrus fruit until now, the ethanolic extract of citrus fruit exhibited in vitro inhibitory effects on melanogenesis in melanoma cells and in vivo prevention against UVB-induced pigmentation of dorsal skin in brown guinea pigs." (PMID 19582213, 2009). "In this study, the anti-melanogenic activity of decapeptide was found to be mediated by inhibiting tyrosinase activity and α-MSH-induced melanin synthesis in B16F10 melanoma cells without inducing cytotoxicity." (PMID 39195491, 2024). "Our results revealed that the water extract of T. himalayense NIBR0000505337 not only effectively inhibited the expression of tyrosinase, TRP-1, TRP-2, and MITF, but also did not exhibit any signs of toxicity in B16F10 melanoma cells at 25, 50, and 100 μg/ml." (PMID 38480002, 2024). "It demonstrated minimal cytotoxicity and decreased tyrosinase activity and melanin levels in B16F10 murine melanoma cells and normal human epidermal melanocytes, regardless of prior cell stimulation by the α-melanocyte-stimulating hormone." (PMID 39598198, 2024). "Treatment with α-melanocyte-stimulating hormone (α-MSH; 150 nM) increased the melanin content of melanoma cells as well as the expression of melanogenic proteins, namely MITF, TYR, and TRP-1,2 compared with that in the negative control (p < 0.05)." (PMID 38338991, 2024). "Hematolymphoid markers (CD45, B cell, and T cell), myogenic markers (myoglobin, desmin, myogenin), melanoma markers (HMB 45, melan A, tyrosinase) and Ewing’s sarcoma markers (CD99/MIC2) are absent in most ONB cases." (PMID 36452830, 2022). "ECPS exhibits anti-melanogenic activity by reducing the expression of tyrosinase, TRP-1, and MITF in B16F10 melanoma cells but has no cytotoxic effect." (PMID 36437391, 2022).
melanoma (continued). "Regarding the IHC markers, the conventional pan-melanoma cocktail, the conventional-adapted pan-melanoma cocktail and, particularly, HMB-45 and tyrosinase, but not melan-A, proved to have an independent prognostic value." (PMID 33801642, 2021). "From the conventional pan-melanoma cocktail members, a significantly higher rate of positivity was highlighted by HMB-45 (92.38%) and tyrosinase (91.42%), but not by melan-A (92.38%) compared to their benign counterpart." (PMID 33801642, 2021). "While N-nicotinoyl dopamine does not inhibit TYR and melanin synthesis in B16F10 mouse melanoma cells, it inhibits melanosome transfer in normal human melanocyte–keratinocyte co-culture systems." (PMID 34360837, 2021). "The independent prognostic value was proved for the conventional pan-melanoma cocktail (triple positivity for HMB-45, melan-A, and tyrosinase) and, independently for HMB-45 and tyrosinase, but not for melan-A, SOX10, or SOX11." (PMID 33801642, 2021). "We further evaluated the gene expression levels of ROPN1, ROPN1B, CTAG1B (identical gene copy to CTAG1A for which no gene expression data is available), TYR and MLANA in 472 additional melanoma samples using data accessible via The Cancer Genome Atlas (TCGA)." (PMID 33918976, 2021). "L-Cysteinamide inhibited TYR-mediated dopachrome formation in vitro and eumelanin synthesis without altering the mRNA and protein expression levels of TYR, TYRP1, and DCT in darkly pigmented human melanoma MNT-1 cells and/or normal HEMs." (PMID 34439449, 2021). "We did not detect transcripts for melanoma antigens, gp100, Dopachrome tautomerase (DCT), Tyrosinase (Tyr), Melan-A and detected low levels of expression of Melanocyte Inducing Transcription Factor (MITF) in SB-3123p cells." (PMID 32231230, 2020). "ECPS exhibitedantimelanogenic activity by down-regulating the expression of tyrosinase, MITF,and TRP-1 without cytotoxic effects in B16F10 melanoma cells." (PMID 29846408, 2018). "This compound did not inhibit directly tyrosinase and its activity was attributed to the inhibition of adenyl cyclase involved in the signalling pathway of α-MSH in B16F10 melanoma cells." (PMID 27829416, 2016). "To clarify the tyrosinase inhibitory effect of PCP on melanogenesis, we determined the intracellular tyrosinase activity of PCP-treated B16F10 melanoma cells with or without α-MSH stimulation." (PMID 26473849, 2015). "On the other hand, 19 out of 23 melanoma samples did not express MITF-M and tyrosinase or expressed low levels of MITF-M but had high levels of expression of miR-155." (PMID 25853464, 2015). "The activity of TYR in MCF-7-TYR cells, positive control melanotic melanoma cells (B16F10) and negative control cells (MCF-7) was measured using their cell lysates, which were incubated with 1 mg/mL of L-DOPA solution for different time frames." (PMID 23508226, 2013). "As opposed to the TYR gene promoter, the activity of the human MIA gene promoter correlates with melanoma progression." (PMID 22649681, 2011). "Tyrosinase, MART-1, and gp100 are melanocyte/melanoma-differentiation antigens that are frequently expressed in melanoma cells and not in non-melanoma tumours." (PMID 20163701, 2010). "In light of our results, the absence of tyrosinase expression in cultured CCS cells is notable, since the tyrosinase promoter is a direct target for Mitf-M in melanoma cells." (PMID 12966428, 2003). "Melanin content and tyrosinase activity assays were conducted to evaluate the effects of 2′-hydroxy-2-methoxychalcone derivatives on melanin synthesis and tyrosinase activity in B16F10 melanoma cells at non-cytotoxic concentrations." (PMID 39996806, 2025). "By immunohistochemical assay, EAML is positive for melanocytic markers such as HMB‐45, melana protein and melanoma antigen recognized by T cells 1 (MART‐1), tyrosinase, and microphthalmia transcription factor but negative for epithelial markers and S‐100 protein." (PMID 38982540, 2024).
melanoma (continued). "Currently, there are no reports on the recovery by cells after tyrosinase inhibition in cells treated with curcumin or its derivatives, except in our previous study where we evaluated the recovery capacity of B16F10 mouse melanoma cells after treatment with PC and CMCs." (PMID 34205035, 2021). "However, further evaluations on the melanin content in murine melanoma B16F10 cells indicated that Thymocid®, at nontoxic concentrations, suppressed the production of melanin while it decreased cellular tyrosinase activity." (PMID 32707654, 2020). "However, 17-AAG, in combination with and without PLX4032, increased the expression of DCT and TYRP1, but not TYR, in all 3/3 BRAFWT melanoma cell lines." (PMID 29481571, 2018). "The protein S-100 is a very sensitive marker for melanoma (expressed in 95% of tumors) but it is not specific and should be used in combination with others markers such as Melan-A, HMB-45 and tyrosinase, which are much more specific (present in 70% of melanomas)." (PMID 27998306, 2016). "Why some melanoma cells appear to express MLANA, but not TYR or MITF, is also not clear, but this hypothesis leads to the prediction that TYR and MITF levels will increase to control levels with time after removal of the melanomas." (PMID 22829910, 2012). "However, the striking finding was that TYR and MITF transcripts were not detectable in patients with melanomas." (PMID 22829910, 2012). "We chose to target the HDGF expression to melanocytes with the help of a Tyrosinase promoter/enhancer element since results presented by Bernard and co-workers revealed HDGF-expression in melanomas whereas HDGF was absent or weakly present in nontumorigenetic melanocytes." (PMID 22014102, 2011). "However, histological findings showed an undifferentiated neoplasm and none of the immunohistochemical stains for melanoma, including S100, HMB-45, Melan A, tyrosinase, CK, CD-34, c-Kit and LCA were able to clarify its origin." (PMID 18445301, 2008). "Although several molecules have some potential clinical values as melanoma biomarkers (lactate dehydrogenase (LDH), tyrosinase, Programmed Cell Death 1 Ligand 1 (PD1L1) and S100B), they also presented some limitations, and for this reason, there is currently no ideal biomarker in melanoma." (PMID 33256110, 2020). "Indeed, tyrosinase activity measured on lysates of tumour tissues was higher in the tumours excised from IGFBP-3-treated mice, confirming the observations made on cultured melanoma cells (not shown)." (PMID 24905466, 2014). "Interestingly, unlike tyrosinase and gp100, which are widely represented in melanoma but also expressed in normal tissues, MAGE-A3 and MAGE-C2, as cancer-germline antigens, are exclusively expressed in germ cells as well as in various types of cancers including, but not limited to, melanoma." (PMID 34696168, 2021).
albinism (115 papers, 2005 to 2025). A congenital disorder characterized by partial or complete absence of melanin pigment in the eyes, hair, or skin. "Many of these loci encompass variants previously linked to retinal layer thickness parameters (including TSPAN10 and LINC00461) while a subset of them has been linked to monogenic disorders, most notably, albinism (including TYR, OCA2 and GPR143)." (PMID 40666342, 2025). "Supporting this, recent work has shown that certain hypomorphic TYR alleles common in European populations contribute to “missing” heritability in mild or undiagnosed albinism." (PMID 40923693, 2025). "In albinism, which is often caused by mutations of tyrosinase and tyrosinase-related protein, various ocular abnormalities, including myopia, decreased choroidal thickness, and decreased visual acuity were observed." (PMID 40591716, 2025). "The role of common genetic variation in pigmentation genes is increasingly recognised, and notably, certain common hypomorphic alleles of TYR have been shown to account for a portion of the missing heritability in individuals with albinism." (PMID 40585125, 2025). "This form of albinism is familiar to the public due to its occurrence in humans, livestock and pets and is caused by mutations in the gene responsible for production of tyrosinase (an enzyme necessary for melanin formation;)." (PMID 40858255, 2025). "Albinism disrupts the tyrosine-to-melanin biochemical pathway due to mutations in genes such as TYR, OA1, and OCA2." (PMID 40125119, 2025). "Patients 11 and 12 had isolated classical albinism confirmed by variants identified in the TYR gene." (PMID 40428344, 2025). "Albinism is a genetic disorder caused by mutations in the TYR gene, leading to impaired TYR production." (PMID 39942712, 2025). "The significantly high rate of TYR gene as the cause of albinism in our population is due to frequent founder pathogenic variants such as c.1037-7T > A (IVS2-7T > A) and c.140G > A (G47D) in in the Ashkenazi and Moroccan Jews respectively." (PMID 39946424, 2025). "A similar scenario is observed with the TYR gene, in which certain variant combinations can cause albinism." (PMID 41272759, 2025). "Molecular genetic diagnosis for most patients started with a next-generation sequencing (NGS) panel targeting genes associated with albinism—TYR, OCA2, MC1R, MITF, SLC45A2, TYRP1, and GPR143—as the initial clinical diagnosis for all patients was albinism." (PMID 39457042, 2024). "In research on pigmentation and albinism, an iPSC line was developed, incorporating two key TYR gene variants, providing a robust in vitro model to explore albinism mechanisms." (PMID 38589876, 2024). "The vast majority of the variants are reported in association with TYR, which is also the most common subtype found in Caucasians and accounts for about 50% of albinism cases worldwide." (PMID 39125459, 2024). "Albinism is an autosomal recessive genetic anomaly that reduces or eliminates melanin production due to a point mutation in the decoding of the TYR gene." (PMID 37238095, 2023). "This reference genome was used to create a variant catalog for the identification of a point mutation in the TYR gene that is associated with albinism and is identical to a causative mutation for OCA1 in the human ortholog." (PMID 37481261, 2023). "Here, the authors study a large albinism cohort and find that a common variant in the TYR promoter contributes to albinism by modifying the penetrance of other common variants, demonstrating a complex genetic architecture." (PMID 35803923, 2022). "Significant odds for a short AL were seen for GPR143-associated ocular albinism (adjusted OR, 56.20; P < 0.001), TYR-associated albinism (adjusted OR, 34.19; P < 0.001), and RPE65-associated disease (adjusted OR, 12.52; P < 0.01)." (PMID 35704304, 2022).
albinism (continued). "We focused on TYR, the gene encoding tyrosinase, and found that a high-frequency promoter variant, TYR c.−301C>T [rs4547091], modulates the penetrance of a prevalent, albinism-associated missense change, TYR c.1205G>A (p.Arg402Gln) [rs1126809]." (PMID 35803923, 2022). "For example, mutations in TYR (Tyrosinase) gene and its related genes can stop melanin synthesis, leading to diluted coat color called albinism in various species." (PMID 36207673, 2022). "OCA1, the most common type of albinism, is caused by bi-allelic mutations in the TYR gene with an estimated prevalence of 1:40,000 globally." (PMID 34360537, 2021). "Specifically, OCA1 consists of a bi-allelic mutation in this TYR gene and happens to be the most common type of albinism." (PMID 33450959, 2021). "Although the role of the TYR R402Q and S192Y hypomorphic alleles in albinism remains controversial, our data suggest that these variants contribute to the extensive inter-individual variability in foveal morphology in the normal population." (PMID 36246950, 2021). "Variations in the TYR gene cause melanin deficiency in human eyes, skin, and hair, resulting in albinism." (PMID 33466315, 2021). "Each of the various mutations in different genes that cause albinism either lead to a reduction of tyrosinase activity and associated loss of L-DOPA production or loss of the receptor for L-DOPA, GPR143." (PMID 32276449, 2020). "Mutations in SLC45A2 can affect the processing of tyrosinase, causing albinism in human eyes and skin." (PMID 32703156, 2020). "Two SNPs in the TYR gene, R402Q (rs1126809) and S192Y (rs1042602), which are frequently reported in association with albinism, were identified in three individuals." (PMID 32411182, 2020). "Using the mouse tyrosinase (Tyr) locus as an experimental model, a gene whose mutations are associated with albinism, we described the chromatin structure in cells at two distinct transcriptional states." (PMID 32968154, 2020). "The present computational analysis provides a theoretical basis for the molecular mechanism of albinism underlying TYR and SLC45A2 gene mutations." (PMID 32849781, 2020). "TYR is commonly known as the albino locus since mutations in this gene result in albinism in several species." (PMID 31249599, 2019). "TYR is commonly known as the albino locus since mutations in this gene result in albinism in several species, including humans." (PMID 31249599, 2019). "Mutations in the tyrosinase (Tyr) gene are known to cause recessive albinism in humans and other species." (PMID 28484254, 2017). "The aim of this study was to identify the genetic mutation responsible for the albinism in a captive capuchin monkey, and to describe the TYR gene of normal phenotype individuals." (PMID 28476152, 2017). "Mutations in TYR in compound heterozygosity result in albinism, developmental stagnation, and autism." (PMID 28977528, 2017). "OCA1 is the most common cause of albinism in European populations and is inherited through autosomal recessive mutations in the Tyrosinase (TYR) gene." (PMID 28667292, 2017). "The C locus mutation implicated in albinism has been identified in the tyrosinase (TYR) gene, which codes for a critical enzyme in melanin synthesis." (PMID 25085922, 2014). "OCA type 1 (OCA1, MIM 203100) is the most severe form of albinism and is caused by mutations in the tyrosinase gene (TYR, MIM 606933; 11q14–q21)." (PMID 25216246, 2014). "Mammalian tyrosinase activity is closely related to skin and hair color, and loss of tyrosinase activity in humans is the direct cause of albinism and leucoderma." (PMID 25071597, 2014). "Microsatellite FCA931, which is closely linked to TYR and TYR sequence variants were tested for segregation with the albinism phenotype." (PMID 16573534, 2006). "In conclusion, we propose that a cytosine deletion in TYR at position 975 in exon 2 is associated with albinism in cats." (PMID 16573534, 2006).